SPO11 (SPO11 initiator of meiotic double strand breaks)
Description:
DNA endonuclease, which specifically mediates DNA cleavage that forms the double-strand breaks (DSB) that initiate meiotic recombination. SPO11 covalently attaches itself to the 5' DNA strand during DSB formation and each strand is cleaved by a composite active site assembled at the interface of two SPO11 monomers, with the two cleavages staggered to produce a two-nucleotide 5' overhang. SPO11 cleavage site selection is driven by a mild sequence bias and a preference for bendable and underwound DNA. Together with TOP6BL, promotes relaxation of negative and positive supercoiled DNA and DNA decatenation through cleavage and ligation cycles. Required for the phosphorylation of SMC3, HORMAD1 and HORMAD2.
Synonyms: CT35; SPATA43; TOPVIA; TOPOVIA
Tractability: No criterion of Open Targets' tractability assessment is met for any kind of drug.
Gene: Protein-coding gene on chromosome 20 (57,329,803 to 57,343,994, forward strand). Ensembl gene ENSG00000054796.
Subcellular location: Chromosome; Nucleus
Pathways (Reactome):
Reproduction: Meiotic recombination
Gene Ontology:
Molecular function: protein binding; DNA binding; DNA endonuclease activity; ATP binding; catalytic activity; DNA topoisomerase type II (double strand cut, ATP-hydrolyzing) activity
Biological process: female gamete generation; meiotic DNA double-strand break formation; meiotic DNA double-strand break processing; reciprocal meiotic recombination; spermatogenesis; DNA metabolic process
Cellular component: chromosome; nuclear chromosome; site of double-strand break; chromosome, telomeric region; nucleus
Genetic constraint (gnomAD): Loss-of-function variants: 14 observed, 17.36 expected, observed/expected ratio (o/e) 0.81, 90% interval 0.53 to 1.26. The upper end of that interval is the gene's LOEUF score, 1.26, which puts it in group 5 of 6, group 1 being the genes least tolerant of losing a copy. Missense variants: 207 observed, 252.89 expected, observed/expected ratio (o/e) 0.82, 90% interval 0.73 to 0.92. Synonymous variants: 105 observed, 93.96 expected, observed/expected ratio (o/e) 1.12, 90% interval 0.95 to 1.31.
Homologues: Orthologues: chimpanzee SPO11 (99% identical), macaque SPO11 (97% identical), pig SPO11 (91% identical), dog SPO11 (90% identical), guinea pig SPO11 (88% identical), mouse Spo11 (83% identical), rat Spo11 (82% identical), rabbit SPO11 (69% identical), tropical clawed frog spo11 (64% identical), zebrafish spo11 (58% identical), Drosophila melanogaster mei-W68 (29% identical), Caenorhabditis elegans spo-11 (24% identical).
Diseases named in the same sentence as SPO11 in open-access papers:
SPO11 is named in the same sentence as 27 diseases in open-access papers, as found by Europe PMC text mining. Sharing a sentence is not in itself a finding about the gene and the disease. The quoted sentences say what the papers report.
male infertility (6 papers, 2015 to 2024). The inability of the male to effect fertilization of an ovum after a specified period of unprotected intercourse. "The Spo11 gene is conserved in humans and single nucleotide polymorphisms of SPO11 are associated with male infertility and decreased ovarian reserve." (PMID 38653846, 2024). "Well designed, unbiased, and large case-control studies should be performed to acquire a more precise association between the SPO11 gene polymorphism and male infertility risk." (PMID 28050928, 2017). "This meta-analysis was performed to provide a clear understanding of the SPO11 C631T gene polymorphisms and risk of male infertility." (PMID 28050928, 2017). "Our present study revealed that SPO11 gene polymorphism significantly associated with male infertility risk, which is in good agreement with previous observations on Chinese population samples." (PMID 28050928, 2017). "Five studies included 1052 individuals, which totally evaluated the influence of SPO11 C631T polymorphism on the risk of male infertility." (PMID 28050928, 2017). "Overall, the results revealed a significant association between the SPO11 C631T polymorphism and male infertility risks (TT + CT vs. CC: OR = 4.14, 95%CI = 2.48–6.89; CT vs. CC: OR = 4.34, 95%CI = 2.56–7.34; T vs. C: OR = 4.35, 95%CI = 2.58–7.34)." (PMID 28050928, 2017). "Several studies have studied the association between SPO11 C631T gene polymorphism and male infertility." (PMID 28050928, 2017). "A previousstudy investigated the association of five single nucleotide polymorphisms (SNPs) in SPO11 gene with male infertility." (PMID 27047561, 2015). "In the present study, we investigated the association of C631T substitution in SPO11 gene with male infertility followed by a novel in silico-analysis." (PMID 27047561, 2015). "In the present study, the overall results showed that SPO11 gene polymorphism could increase the risk of male infertility (TT + CT vs. CC: OR = 4.14, 95%CI = 2.48–6.89; CT vs. CC: OR = 4.34, 95%CI = 2.56–7.34; T vs. C: OR = 4.35, 95%CI = 2.58–7.34)." (PMID 28050928, 2017). "Our results of this meta-analysis suggest that genetic variations of SPO11 C631T may contribute to susceptibility to male infertility." (PMID 28050928, 2017). "In summary, this meta-analysis provides evidence that the SPO11 C631T polymorphisms may contribute to genetic susceptibility to male infertility risk." (PMID 28050928, 2017). "Therefore, to evaluate the relationship between the SPO11 C631T gene polymorphism and risk of male infertility, we have conducted a meta-analysis from all relevant scientific literatures." (PMID 28050928, 2017). "The pooled results indicated that the SPO11 gene C631T polymorphism was significantly associated with increased risk of male infertility (TT + CT vs. CC: OR = 4.14, 95%CI = 2.48–6.89; CT vs. CC: OR = 4.34, 95%CI = 2.56–7.34; T vs. C: OR = 4.35, 95%CI = 2.58–7.34)." (PMID 28050928, 2017). "In conclusion, this study suggested that SPO11 gene C631T polymorphism may contribute as a genetic factor susceptible to cause male infertility." (PMID 28050928, 2017). "It been shown that in rats, a disrupted SPO11 gene can causes male infertility." (PMID 27047561, 2015). "Subgroup analysis of different countries proved the relationship between SPO11 gene C631T polymorphism and male infertility risk in Chinese, but not in Iranian peoples." (PMID 28050928, 2017). "Several studies suggest the SPO11 gene as a candidate gene for male infertility." (PMID 28050928, 2017). "The disruption of SPO11 gene in mouse by homologous recombination leads to severe gonadal abnormalities from defective meiosis and apoptotic death during early prophase, resulting in male infertility." (PMID 28050928, 2017). "In addition, at least two putative genes related to male infertility, CTCFL and SPO11, are located in the middle of the region detected on BTA13 (13:58456868–59951247)." (PMID 27842509, 2016).
infertile (5 papers, 2013 to 2021). "have studied SPO11 gene polymorphism in 100 infertile and100 fertile men in Iran." (PMID 28050928, 2017). "Therefore any change or mutation in SPO11 gene can cause infertility in men." (PMID 27047561, 2015). "Therefore, any change or mutation in SPO11 gene may cause infertility in men." (PMID 28050928, 2017). "Identical to the Spo11 knockout, male and female Spo11YF/YF mice are infertile, and leptotene and zygotene nuclei display global absence of markers of DSB formation and repair." (PMID 23754961, 2013). "The mutation of mouse Spo11 caused infertility due to arrested spermatocyte with no synapsis, suggesting a role of Spo11 in maintaining synapsis during spermatogenesis." (PMID 34769330, 2021). "The arrest is not likely due to the failure to repair Spo11-induced DSBs since the spo11–/–rad21l1–/– population develops as infertile males." (PMID 34692709, 2021). "Although many studies have been done on the biological role of SPO11 gene but its role in infertility has not been studied extensively yet." (PMID 27047561, 2015).
cyst (4 papers, 2020 to 2024). A sac-like closed membranous structure that may be empty or contain fluid or amorphous material. "Mutation of the Tyr residue for the active site or two conserved residues corresponding to key DNA-binding residues for Arabidopsis Spo11 reduced the levels of cwp1-3 and myb2 gene expression and cyst formation." (PMID 34769330, 2021). "Our findings from targeted disruption of the spo11 gene indicate that Spo11 can induce expression of cwp1-3 and myb2, and cyst generation, thereby inducing encystation." (PMID 34769330, 2021). "In this sense, in Spo11-/- ovaries, Chk2 mutation preferentially rescues the number of oocytes in cysts, supporting the idea that DDR impacts cyst breakdown, and consequently follicle formation." (PMID 33206637, 2020). "Interestingly, overexpression of Spo11 resulted in increased expression of cwp1-3 and myb2 genes and cyst formation." (PMID 34769330, 2021). "Our results suggest that Spo11 can induce the cwp1-3 and myb2 gene expression and cyst production." (PMID 34769330, 2021). "Our results suggest that Spo11 acts as a positive regulator for Giardia differentiation into cyst." (PMID 34769330, 2021). "In addition, the Spo11m1-HA- and Spo11m2-HA-expressing cell lines displayed significant reduction in cyst number compared to the wild type Spo11-HA-expressing cell line." (PMID 34769330, 2021). "We found evidence of Spo11 in inducing expression of cwp1-3 and myb2 genes and cyst generation, providing insights into the role of Spo11 in inducing Giardia differentiation into cyst." (PMID 34769330, 2021). "In addition, the Spo11-HA-expressing cell line exhibited a significant increase in the cyst number." (PMID 34769330, 2021). "Furthermore, the majority of germ cell clusters that sharply express PRDM9 and SPO11 might undergo apoptosis after cyst breakdown, leading to germ cell attrition." (PMID 33372178, 2020). "Targeted disruption of spo11 gene with CRISPR/Cas9 system led to a significant decrease in cwp1-3 and myb2 gene expression and cyst number." (PMID 34769330, 2021). "RAD21, SMC3, and MEI2 are linked to bloom-promoting sex, HOP2 and MSH4 to cyst germination, while SPO11, MND1, and DMC1 are common to both cyst-forming and non-encysting sex." (PMID 39367346, 2024). "Interestingly, in the Spo11-HA positive stained cells, the CWP1 protein was stained in the encystation secretory vesicles (ESVs), which are responsible for transportation of CWPs to cyst wall, suggesting that Spo11 may function in inducing the ESV and thereby in inducing cyst formation." (PMID 34769330, 2021). "Interestingly, the ablation of CHK2 in Spo11-mutant mice selectively rescued oocytes in cysts (p = 0.0025, T-test), suggesting that CHK2 activity is required for the cyst breakdown, at least in the absence of SPO11." (PMID 33206637, 2020).
female infertility (3 papers, 2012 to 2025). Diminished or absent ability of a female to achieve conception. "Deletion of Spo11 causes both male and female infertility in mice due to checkpoints that eliminate germ cells failing to engage in meiotic recombination, synapsis, and silencing." (PMID 41092908, 2025). "Disruption of SPO11 expression results in both male and female infertility in mice." (PMID 34360715, 2021).
cervical cancer (2 papers, 2013 to 2016). A primary or metastatic malignant neoplasm involving the cervix. "Interestingly, both PRDM9 and SPO11 expression has been demonstrated in multiple cancer cell lines, and SPO11 is expressed in melanoma and cervical cancer tumors." (PMID 27275820, 2016). "In addition, ectopic expression of some key meiotic genes was also reported in primary tumours, for example MOS in NSCLC, DMC1 in cervical cancer, SPO11, REC8, SGO1 and HORMAD1 in melanoma." (PMID 24025698, 2013).
endothelial dysfunction (2 papers, 2024). In vascular diseases, endothelial dysfunction is a systemic pathological state of the endothelium (the inner lining of blood vessels) and can be broadly defined as an imbalance between vasodilating and vasoconstricting substances produced by (or acting on) the endothelium. "Moreover, research has linked the BMP7 gene to diabetes and vascular calcification in humans, while the SPO11 gene has been linked to endothelial dysfunction resulting from exercise-induced DNA damage in horses." (PMID 39118059, 2024). "These factors also favor DNA damage, thereby linking SPO11 to endothelial dysfunction." (PMID 38885195, 2024).
melanoma (2 papers, 2013 to 2016). A malignant, usually aggressive tumor composed of atypical, neoplastic melanocytes. "Melanomas have also been shown to express meiosis specific proteins including SCP1 (homologous chromosome pairing), HORMAD1 (meiotic synapse regulation), SPO11 (double stranded DNA breaks), and REC8 (meiosis cohesion protein)." (PMID 23840955, 2013). "Both SPO11 and HORMAD1 have been specifically noted in melanoma and we found them to be overexpressed in melanoma compared to nontransformed cell types using western blot analysis and immunofluorescence." (PMID 23840955, 2013).
breast carcinoma (1 paper, 2016). "In addition, the human SPO11 gene is found in chromosome 20q13.2–13.3, a region that is amplified in multiple breast cancers and associated with genomic instability, such as aneuploidy, in breast cancer." (PMID 27275820, 2016).
hydatidiform mole (1 paper, 2021). A gestational trophoblastic disorder characterized by marked enlargement of the chorionic villi, hyperplasia of the villous trophoblastic cells and hydropic changes. "Recent studies have found biallelic variants of MEI1 and SPO11 in males with familial nonobstructive azoospermia, and variants of TOROVIBL, MEI1, and REC114 in females with recurrent miscarriage and hydatidiform moles." (PMID 34257419, 2021).
ovarian carcinoma (1 paper, 2010). A malignant neoplasm originating from the surface ovarian epithelium. "RT-PCR products for the incomplete sequence of human SPO11 were also observed in several types of cancer cells from prostate, colon and ovarian carcinomas and SPO11 is a known cancer testis antigen." (PMID 24710101, 2010).
ovarian failure (1 paper, 2010). "In contrast to other critical genes during meiosis, such as Dmc1, Msh5, Spo11 and Atm that cause early ovarian failure due to rapid loss of oocytes following disruption of meiosis I, Hormad1 deficiency does not activate apoptotic pathways and does not lead to gross premature loss of oocytes." (PMID 21079677, 2010).
prostate carcinoma (1 paper, 2018). A carcinoma that arises from epithelial cells of the prostate gland. "SPO11 expression is limited to male tissues like CTCFL; the combined expression of these genes in sperm cells is reminiscent of reduced fertility phenotypes associated with CTCFL deficiency in mice and prostate cancer." (PMID 29385718, 2018).
Renal cyst (1 paper, 2025). A fluid filled sac in the kidney. "Further examination of differentially expressed genes in renal cysts and SC transplants demonstrated significant downregulation of key meiotic proteins, including Sycp3 and Sycp1, as well as defects in DSB-related proteins Rad51 and Spo11, which align with our previous findings." (PMID 40386496, 2025).
cancer (13 papers, 2010 to 2023). A tumor composed of atypical neoplastic, often pleomorphic cells that invade other tissues. "The SPO11 protein may have diagnostic, prognostic, and therapeutic value in cancer treatment." (PMID 36816926, 2023). "SPO11 knockdown in various cancer cell lines results in reduced proliferation and altered cell cycle dynamic." (PMID 36816926, 2023). "Given all this, these four DDR genes (EME2, MSH4, MLH3, and SPO11) have been proved to take part in the pathogenesis, progression, and prognosis of cancers." (PMID 36816926, 2023). "One of the identified target genes is meiotic W68 (mei-W68), the Drosophila orthologue of the human cancer/testis gene Sporulation-specific protein 11 (SPO11), the enzyme that catalyses the formation of meiotic double-strand breaks." (PMID 28855394, 2017). "SPO11 may play a critical role in genome stability control and be essential for cancer progression." (PMID 36816926, 2023). "Therefore, it can be speculated that activation of meiotic programs in cancer cells may contribute to genome instability, and that meiosis-specific CT antigens, such as SPO11, SCP1 and HORMAD1, may be involved." (PMID 26158218, 2015). "SPO11 is instrumental to meiotic chromatid exchange of genetic material by producing double strand breaks and might promote chromosomal rearrangements in cancer cells by a similar mechanism." (PMID 26158218, 2015). "mei-W68 is the Drosophila orthologue of SPO11, a human cancer/testis gene catalogued as CT35 that is aberrantly expressed in different types of cancer." (PMID 28855394, 2017). "Although there is no data specifically implicating these pathways in cancer, it is important to note that SPO11, DMC1, and HORMAD1 have all been shown to be increased in cancer." (PMID 23840955, 2013). "Somatic mutations in genes within narrow MCR, including FLT4, MAPK9, SPO11 and KHDRBS2, have been reported in cancers (COSMIC v48 release)." (PMID 21151896, 2010). "A number of meiosis-specific CT genes including, but not limited to SPO11, STRA8, DMC1, REC8, STAG3, SGO2, SYCP1/2/3 and HORMAD1 have been shown to be expressed in various solid and hematological cancers as well as in different cancer cell lines." (PMID 30701021, 2018). "For SPO11 and PRDM9, which induce DNA strand breaks and create crossover events in cancer cells, one can speculate that their activation in cancer cells drives genomic instability and might therefore increase the sensitivity of these cells to DNA-damaging agents." (PMID 35251135, 2022).
tumour (5 papers, 2006 to 2022). "In particular, polyploid tumor cells can undergo depolyploidization that is accompanied by upregulation of SPO11 and REC8 genes." (PMID 31558727, 2019). "The finding of Mei-W68/SPO11, the endonuclease that forms DSBs during meiosis, as an efficient suppressor of mbt tumour growth provides the first experimental evidence for the long suspected pro-tumoural role of mei-W68/SPO11." (PMID 28855394, 2017).
SPO11 also shares sentences with these, for which no sentence is quoted: malaria (2 papers); chronic fatigue syndrome (1); cutaneous T-cell lymphoma (1); diabetes (1); endocrine disorder (1); gastric cancer (1); generalized epilepsy (1); malignant brain tumour (1); panic disorder (1); personality disorder (1); Pseudoxanthoma elasticum (1); Sezary syndrome (1).